MET (MET proto-oncogene, receptor tyrosine kinase)
Diseases named in the same sentence as MET in open-access papers (continued):
Sharing a sentence is not in itself a finding about the gene and the disease.
tumor (continued). "In one of the four SCLC tumour tissues (25%) screened, preferential c-MET overexpression and activation of p-MET (both the phosphoepitopes pY1003 and pY1230/1234/1235) along the tumour expanding invasive front were identified." (PMID 17667909, 2007). "We have also examined in details the topographic distribution of the various phosphoproteins in the c-MET/HGF pathway in SCLC tumour tissue." (PMID 17667909, 2007). "Here, c-MET is found to be preferentially overexpressed and activated along the peripheral tumour invasive front." (PMID 17667909, 2007). "Phosphoantibody-based immunohistochemical analysis of SCLC tumour tissue and microarray established the role of c-MET in SCLC biology." (PMID 17667909, 2007). "We also studied the role of c-MET/HGF signalling pathway in SCLC tumour tissues using phosphospecific antibodies IHC analysis with focus on its topographic pattern of expression." (PMID 17667909, 2007). "This supports a role of c-MET activation in tumour invasive front in the tumour progression and invasion involving FAK and AKT downstream." (PMID 17667909, 2007). "We confirmed that VEGF-A, TGFβ, EGF-R and c-MET were all highly expressed in tumour tissue, and correlated positively with tumour grade." (PMID 16465195, 2006). "In tumour tissue, the levels of RNA transcripts for MET are 10–100-fold higher than in the surrounding normal thyroid." (PMID 15266330, 2004). "To address the paucity of tools for directly measuring MET activation in tumor cells within patient biopsy specimens, we developed a robust, quantitative immunofluorescence microscopy assay to measure levels of pY1235MET and total MET in in vitro, in vivo, and patient tumor specimens." (PMID 42118765, 2026). "Anti‐angiogenic TKIs can normalize tumor vasculature, enhance T effector cell infiltration, and reduce immunosuppressive myeloid cells, while MET inhibition may further modulate antitumor immunity via VEGF‐axis regulation and macrophage activation." (PMID 41259021, 2026). "Finally, our comparative analysis of T cell-mediated tumor cell killing in co-cultures of tumor cells and peripheral blood mononuclear cells (PBMCs) demonstrated equal efficacy for taFv-cMET and scDb-cMET in co-cultures with c-MET+ target cells." (PMID 41552759, 2026). "Expression of MET from tumor slides were assessed by immunofluorescence." (PMID 39980226, 2025). "In summary, c-MET–centered combination therapy strategies in OS encompass a broad spectrum of interventions, including small-molecule inhibitors, non-coding RNAs, biological regulatory axes, and modulation of the tumour immune microenvironment." (PMID 40599602, 2025). "However, abnormal activation of the c-MET signaling pathway often occurs during cancer development, promoting the growth, invasion and metastasis of tumour cells." (PMID 40078386, 2025). "Increased expression of MET was observed in both the primary tumor and metastasis (93.5 and 84.1%)." (PMID 40299443, 2025). "Based on these, we suggested that miR-130b and MET may be potential anti-tumour targets for new treatment of PC." (PMID 38607540, 2025). "However, the degradation of total c-MET was observable when tumor cells were incubated with AS1411-SL1 chimeras at concentrations exceeding 500 nM." (PMID 39744222, 2025). "Furthermore, MET increases in the gene copy number (GCN) can occur with polyploidy, the duplication of chromosomes, with multiple copies of chromosome 7 (where the MET gene resides) present in tumor cells." (PMID 40725428, 2025). "Unlike myCAF, iCAF is enriched in early stage ICC and promotes ICC development through the hepatocyte growth factor (HGF)-MET (HGF receptor) axis as a key tumor-promoting ligand–receptor pair, directly linking iCAF to tumor cells via ERK-mediated tumor cell proliferation." (PMID 40248197, 2025).
tumor (continued). "Additionally, preclinical studies have demonstrated that inhibition of the HGF/MET pathway suppresses tumour growth in multiple cancer models and, in some cases, overcomes resistance to other anticancer agents." (PMID 40599602, 2025). "Staining patterns for all selected markers, including CEA, EpCAM, c-MET and EGFR, were predominantly heterogeneous in both tumor and adjacent normal epithelium, exhibiting intra- and inter-sample variations, whereas c-MET staining was mostly homogeneous (intra-sample variation) in normal tissues." (PMID 40563608, 2025). "Moreover, the AS1411-SL1 chimeras effectively degraded c-MET in tumor cells that were resistant to traditional inhibitors." (PMID 39744222, 2025). "c-MET specific inhibitor PHA-665752 as well as two other FDA-approved drugs, crizotinib and cabozantinib, selectively inhibited the growth of ARID1A-deficient CRC cells in vitro and in xenograft tumor models." (PMID 40369167, 2025). "Compared with MET WT, METΔex14 cells injected into the mouse tail vein displayed increased tumor growth and metastasis to the lungs and brain, potentially driven by enhanced extracellular matrix remodeling, cytoskeletal reorganization, and focal adhesion formation." (PMID 40924941, 2025). "Our data suggest that CEA and c-MET, recognized as the most promising targets, may effectively distinguish tumor from surrounding normal tissue, in our study in about half of the evaluated specimens." (PMID 40563608, 2025). "MET activation (inclusive of amplification and METEx14 mutations) was observed in 6.9% of ERBB2amp NSCLC and showed comparable prevalence in GEC between ERBB2amp and ERBB2mut tumors (5.5% and 6.0%, respectively), being less common in other tumor types." (PMID 40178042, 2025). "Due to the reported high tumorigenic and invasive potential of Met-expressing cells, and more permissive conditions of the TME upon pericyte depletion, we postulated that MET+ cells are among the main drivers of the observed aggravated tumor progression in Pdgfbret/ret mice." (PMID 41339360, 2025). "This QSP model was rigorously calibrated and validated by referencing extensive experimental datasets (including data on signal transduction, cell viability, pharmacokinetics, tumor growth inhibition and clinical-level treatment response) for over 15 different candidate drugs for MET-aberrant NSCLC." (PMID 41368576, 2025). "The amplification of chromosomal regions containing the genes EGFR, MET, KIT, and PDGFRA is associated with the receptor tyrosine kinase (RTK) and growth-factor receptors, often driving proliferative and angiogenic signalling in tumours." (PMID 41573648, 2025). "In cohort D of the CHRYSALIS-2 study, the combination therapy of amivantamab and lazertinib reported an ORR of 61% and mPFS of 12.2 months in patients with MET-positive (MET 3 or higher staining in ≥25% tumor cells) EGFR-mutant NSCLC progression on osimertinib." (PMID 40470164, 2025). "The recurrent tumor specimen also showed an acquired MET copy gain." (PMID 41155159, 2025). "The HGF/MET pathway has been identified as a critical role in tumor-stroma interactions." (PMID 39926258, 2025). "In this study, both PDGCOs_1 and PDGCAs_1 were sensitive to the MET inhibitor crizotinib, likely reflecting a tumor-intrinsic sensitivity in patient 1’s epithelial cells that permitted effective drug targeting, even in the presence of stromal-mediated resistance to other agents." (PMID 40723172, 2025). "Dual-targeting nanohybrids that combine GalNAc (hepatocyte targeting) and c-MET inhibitors (tumor targeting) in lipid–polymer hybrids could enhance OC’s specificity." (PMID 40564985, 2025). "c-MET signaling is thought to play a crucial role in promoting the development and maintenance of the tumor microenvironment, facilitating immune evasion by tumor cells and enabling them to escape T-cell-mediated killing." (PMID 40520181, 2025).
tumor (continued). "Due to the presence of the MET variant in the cfDNA, we wanted to determine whether the patient’s tumor biopsy sample possesses MET activity." (PMID 40386554, 2025). "There was a trend for higher MET protein/RNA-ISH in CMS4 tumours." (PMID 40211189, 2025). "c-MET is a RTK commonly overexpressed in RCC and linked to tumor growth and metastasis." (PMID 41019287, 2025). "Consequently, this sustains activation of the MET signaling pathway, promoting tumor cell growth and dissemination." (PMID 40710213, 2025). "The results suggested that the c‐MET inhibitor JNJ‐38877605 could significantly inhibit the growth of transplanted tumours with CPNE3‐overexpressing cells in nude mice." (PMID 41190648, 2025). "Under the selective pressure of first- and third-generation EGFR-TKIs, tumor cells can adapt through on-target alterations (for example, T790M or C797S), as well as via bypass-track activation, such as MET amplification, HER2 or AXL upregulation, and reactivation of downstream signaling." (PMID 41472727, 2025). "This revealed that tumor cells in MBMs not only exhibited significantly upregulated tumorigenesis and maintenance genes (e.g., MET and TBX2), but also expressed neural differentiation markers (e.g., NRG3, NELL1, NCAM1, ADNP) and cell adhesion molecules (e.g., CDH1, PRKCA)." (PMID 41284647, 2025). "This dissociation significantly enhances the internalisation of MYTX‐011 into c‐MET+ tumour cells." (PMID 40619749, 2025). "The RTK c-MET drives tumor invasiveness and metastasis, including advanced PCa." (PMID 41470892, 2025). "This suggests that FGFR1-driven MIBC are characterized by HGF-rich tumor microenvironments, which may promote the expansion of MET-amplified subpopulations within heterogeneous tumors during erdafitinib treatment." (PMID 41315241, 2025). "The expression of MET was increased in both the primary tumor and metastatic sites; however, phosphorylation was significantly upregulated in metastasis compared with the primary tumor." (PMID 40299443, 2025). "Combined inhibition of FGFR1 and MET significantly suppressed tumor growth in resistant cells." (PMID 41315241, 2025). "Taken together, these findings demonstrate that MET activation positively correlated with the infiltration of GITR+ Tregs in PDAC, highlighting a potential mechanism by which tumor‐intrinsic MET signaling may drive immune evasion through Treg reprogramming." (PMID 40673866, 2025). "In contrast, the MET‐high subtype is characterised by high MET expression and, thus, is potentially responsive to small‐molecule tyrosine kinase inhibitors; the lack of immunocyte infiltration suggests this subtype is a ‘cold’ immune tumour type." (PMID 39828982, 2025). "The full QSP model is comprised of a cell signaling module and multiple drug pharmacokinetics (PK) modules to systematically describe the mechanisms by which MET pathway dysregulation promotes tumor growth and how targeted pathway interventions inhibit tumor growth." (PMID 41368576, 2025). "Telisotuzumab Vedotin, an antibody-drug conjugate with MET as the target, was recently approved (based on the LUMINOSITY trial) to treat NSCLC patients with high MET protein overexpression (≥50% of tumor cells with strong/3+ staining) who have received a prior systemic therapy." (PMID 41368576, 2025). "Of specific interest in this case is the MET mutation that, together with the corresponding protein activation in the tumor tissue, suggests that MET inhibitors could be explored as a targeted therapeutic strategy." (PMID 40386554, 2025). "Cross-tumor evidence supports MET as a key factor in the formation of metastatic niches." (PMID 40860829, 2025).
tumor (continued). "Initially, the study included patients with MET amplification/overexpression (IHC 3+ expression in ≥50% of tumor cells or FISH GCN ≥ 5) in patients on progression on any line of osimertinib (≤3), determined by means of liquid or tissue biopsy and centrally confirmed." (PMID 40725428, 2025). "Furthermore, c-MET controls cancer cell proliferation, survival, motility and invasion that, when dysregulated by anomalous c-MET activation, can lead to tumour growth and metastatic progression of cancer cells." (PMID 40650165, 2025). "Our in vivo results are therefore consistent with the in vitro experiments and suggest that not only do ETV1 and ERG promote the formation of larger tumours, but that MET also participates in these effects, notably observed by the reversal of ETV1/ERG‐induced tumour progression by Capmatinib." (PMID 39374163, 2025). "In addition, apatinib also suppresses c-kit, c-Src, platelet-derived growth factor receptor-β, and MET, thus directly exerting the anti-tumor effects." (PMID 40837644, 2025). "Despite these advancements, the issue of non-selectivity remains, as these PROTACs are not tumor-specific and do not fully alleviate the safety concerns associated with conventional c-MET inhibitors." (PMID 39744222, 2025). "Teliso-V binds with high affinity to tumor cells expressing c-MET." (PMID 41189945, 2025). "Agents targeting the HGF/c-MET axis have shown clinical efficacy across multiple tumor types." (PMID 40520181, 2025). "Additionally, IHC assays demonstrated that RNASET2 expression was lower in HCC tumor tissues compared to adjacent non‐tumor tissues, but MET expression was found to be elevated in the tumor tissues." (PMID 39903758, 2025). "Ongoing clinical trials are evaluating the efficacy of MET tyrosine kinase inhibitors in various solid tumor types to determine whether MET alterations can be considered a tumor-agnostic target (NCT02978261, NCT03993873, and NCT01639508)." (PMID 39658086, 2025). "Importantly, while the METY1230S mutation has been previously identified in patients and pre‐clinically characterised, this is the first time that the clinical activity of a type II MET inhibitor against a tumour harbouring this MET alteration is reported." (PMID 40437874, 2025). "The MET gene encodes a receptor tyrosinekinase, and its amplification has been linked to reduced STING expression, whichcompromises interferon responses and inhibits anti-tumor immunity." (PMID 40985687, 2025). "PROTACs targeting c-MET have displayed improved antitumor efficacy by overcoming drug resistance, whereas safety concern caused by lack of tumor-targeting ability is still a pending issue." (PMID 39744222, 2025). "Yet in contradiction, comparative MET-dependent and MET-independent cell-based studies on tivantinib have also shown MET agnostic anti-tumor activity, posing that tivantinib may have an alternative inhibitory mechanism than an MET-selective one." (PMID 39960754, 2025). "They observed MET mRNA expression in 88% of tumors (22 of 25 tumor samples)." (PMID 40649874, 2025). "Yet in contradiction, comparative MET-dependent and MET-independent cell-based studies on tivantinib have also shown MET agnostic anti-tumor activity, posing that tivantinib may have an alternative inhibitory mechanism than a MET-selective one." (PMID 39071407, 2024). "Strikingly, the patient tumor at second progression on osimertinib, although classified as MET polysomy (mean MET copies 4.8 and MET/CEP7 ratio of 1.5), showed approximately 26% MET amplified cells and focal areas with positive membranous phospho-MET staining (middle)." (PMID 38276867, 2024). "Moreover, c-MET inhibition decreases the recruitment of neutrophils into the T cell–inflamed tumor microenvironment and draining lymph nodes in response to cytotoxic immunotherapies." (PMID 38909206, 2024).
tumor (continued). "We therefore suggest that the activation of MET- or STAT3-mediated signaling processes or those related to stress/senescence or inflammation strongly depends on the composition of the tumor microenvironment, likely determining the response to therapeutic interventions." (PMID 38386085, 2024). "Tepotinib, a MET inhibitor, targets the MET pathway involved in tumor growth and metastasis." (PMID 39275127, 2024). "The promotion of cell death and inhibition of cell proliferation by c-MET knockdown indicated that it could serve as a tumor driver gene." (PMID 38352883, 2024). "Particularly, c-MET expression in neutrophils has been shown to be required for their transmigration and nitric oxide release in inflamed tumors, which are essential for tumor cell killing." (PMID 38909206, 2024). "Fortunately, current preclinical evidence in the listed studies suggested that tumor cells harboring MET fusions showed sensitivity to treatment with MET-TKIs, such as crizotinib, tepotinib, SGX523 and foretinib, indicating the basis for treatment methods for patients harboring MET fusions." (PMID 38195556, 2024). "As subclonal MET amplification may be evident in MET polysomy tumor progression, MET polysomy warrants close clinical follow-up with phospho-MET IHC in parallel with FISH diagnostic." (PMID 38276867, 2024). "While MET-CAR.CD28ζ is favored for future advancements, optimizing the CAR construct design and implementing strategies to counteract CAR-T cell exhaustion induced by the tumor microenvironment are essential to enhance the therapeutic efficacy of MET-CAR-T cells." (PMID 39569202, 2024). "MET amplification is thought to drive overexpression of the MET receptor and its constitutive, ligand-independent activation, thereby dysregulating the MET pathway and promoting tumor growth." (PMID 39356253, 2024). "Nineteen DNA samples that were positive for METex14 variants had SNVs and deletions in the region of the splice donor (SD) site, and, interestingly, the analysis of these tumor biopsies (TBx) showed up two SNVs at the splice region of MET (affected DNA regions in red)." (PMID 39769478, 2024). "Taken together, our data demonstrate that during the early stage of EGFR-targeted therapy, tumor cells can rapidly develop tolerance to osimertinib without acquiring new resistant mutations or activating MET." (PMID 39041204, 2024). "In addition to overexpression, MET can also influence tumor growth via over-activation, MET gene amplification, fusion of MET with another gene, or mutations that activate MET." (PMID 39062731, 2024). "In both normal and tumor cells, Akt, Erk1/2, and Stat3 are known targets of MET signaling." (PMID 38596618, 2024). "Despite that, there is supporting preclinical data that suggests Cabozantinib could potentially inhibit tumor growth in NEPC harboring MET alterations or increased expression levels." (PMID 38543137, 2024). "This further supports the hypothesis that circulating EMI-137 binds specifically to MET-expressing PTC tumor cells." (PMID 38017325, 2024). "Together, these findings underscore the critical role played by tumor heterogeneity and the microenvironment in determining drug response while uncovering the molecular mechanisms behind acquired drug resistance to targeted therapy against MET." (PMID 38596618, 2024). "The HGF/MET/CD44v6 signaling pathway promotes tumor growth and metastasis in pancreatic cancer." (PMID 39769452, 2024). "In summary, ABBV-399 (telisotuzumab vedotin, Teliso-V) represents a promising advancement in targeting c-MET-overexpressing tumor cells, demonstrating significant antitumor activity across various preclinical models, including those resistant to other c-MET inhibitors." (PMID 39664377, 2024). "Furthermore, systemic treatment with c-MET inhibitors curtailed the recruitment of TANs, ultimately impacting tumor growth and volume more significantly than MET knockdown in cancer cells." (PMID 39664377, 2024).